BMP2 (bone morphogenetic protein 2)
Diseases named in the same sentence as BMP2 in open-access papers (continued):
Sharing a sentence is not in itself a finding about the gene and the disease.
liver cancer (continued). "Besides, BMP2 has been shown to inhibit liver cancer cell migration and growth by downregulating PI3K/AKT signaling." (PMID 29416020, 2018). "In previous study, we found that BMP-2 silence could inhibit liver cancer cell’s proliferation, migration and invasion by down-regulation of MMP2 and MMP9 through MAPK/ERK pathway." (PMID 27886213, 2016). "In previous study, we found that BMP-2 could promote liver cancer cell’s proliferation and migration, and played an important role in liver cancer invasion through down-regulation of MMP2 and MMP9." (PMID 25002834, 2014). "However, the impact of BMP2 on the malignancy of liver cancers was very rarely investigated." (PMID 32195173, 2020). "However, other studies have also shown that BMP2 signaling could inhibit the proliferation and migration of liver cancer cells." (PMID 32195173, 2020). "We found that BMP2 within the circulation could promote the expansion of MDSCs in peripheral blood, and the infiltration of MDSCs in tumor, which resulted in the promoted liver cancer growth." (PMID 32195173, 2020). "Furthermore, BMP2 signaling-activated MDSCs could secrete IL6 to enhance cell proliferation of liver cancer cells in vitro and facilitate liver cancer growth in vivo." (PMID 32195173, 2020). "However, it has been unclear whether BMPs directly promote vascular endothelial cell proliferation and its mechanism in liver cancer, and moreover little research has been done regarding the role of BMP-2 in HCC angiogenesis." (PMID 27886213, 2016). "In this study, Se-Y significantly downregulated the expression of BMP2, FGF9, and HEY1 in the liver, indicating that it can prevent liver cancer in laying hens." (PMID 37570275, 2023). "In our results, BMP2 signaling activated MDSCs to secrete IL6, further enhancing liver cancer cell proliferation." (PMID 32195173, 2020). "More importantly, we observed that BMP2 activated MDSCs to secrete IL6, which directly enhanced the proliferation of liver cancer cells." (PMID 32195173, 2020). "Moreover, intravenous injection of rhBMP2 and implantation of rhBMP2 collagen gels in tumor-burdened mice could increase the IL6 levels in both peripheral blood and tumor tissues, indicating that MDSC expansion, induced by BMP2, enhanced liver cancer growth via IL6." (PMID 32195173, 2020). "Thus, BMP2 signaling might promote liver cancer growth indirectly via the activation of MDSCs." (PMID 32195173, 2020). "BMP2 activated MDSCs to secrete IL6, further enhancing liver cancer cell proliferation." (PMID 32195173, 2020). "However, we found that BMP2 did not promote the proliferation of liver cancer cells directly in vitro." (PMID 32195173, 2020). "In our results, we found that BMP2 signaling could enhance the expression of the Arg1 and IL6 in bone marrows, rather than iNOS, IL8, and IL10, indicating that BMP2 inducing MDSCs expansion might enhance liver cancer growth via IL6." (PMID 32195173, 2020). "Gpc3 has been reported to modulate WNT and HH signaling in liver cancer and interestingly, GPC3 was previously found to interact with BMP2, like the not differentially expressed GPC1, to regulate suture fusion." (PMID 37378024, 2023).
myocardial infarction (10 papers, 2015 to 2025). Gross necrosis of the myocardium, as a result of interruption of the blood supply to the area, as in coronary thrombosis. "Indeed, GREM2-dependent control of BMP2 availability affects the extent of immune cell infiltration and maintenance of heart function during experimental myocardial infarction in Grem2-deficient mice." (PMID 39196111, 2024). "We induced myocardial infarction in Wistar rats by permanent ligation of the left coronary artery and showed a change in the expression pattern of Notch-associated genes and Bmp2/Runx2 in post-MI tissues using RNA sequencing and RT-PCR." (PMID 35740305, 2022). "In the study of myocardial infarction, BMP2 performs early induction of protein expression in both cardiomyocytes and interstitial fibroblasts." (PMID 39334820, 2024). "BMP signaling is also involved in development, and according to our data, it is activated during myocardial infarction, in particular, Bmp2." (PMID 35740305, 2022). "The expression of BMP-2 is increased after myocardial infarction, not only anti-apoptosis, but also regulating the cardiomyocyte differentiation of cardiac progenitors." (PMID 29482607, 2018). "Just recently, a cardioprotective role in myocardial infarction has been shown for another TGFβ-family member, namely BMP2." (PMID 25788886, 2015). "Now it has been proven that activation of this pathway by a single bolus injection of BMP2 post-myocardial infarction is able to reduce apoptotic cell death of cardiomyocytes and improves cardiac function, although mortality rates of mice were not affected." (PMID 25788886, 2015). "ScRNA-seq data have revealed that BMP2 expression is specific to the embryonic period when angiogenesis is active, and reactivation of BMP2 can induce endocardial angiogenesis in neonatal mouse models of myocardial infarction." (PMID 40121354, 2025). "BMP2 was also shown to induce endocardial angiogenesis in neonatal mice post-myocardial infarction." (PMID 38028463, 2023). "Expression of Bmp2 has been observed in both cardiomyocytes and interstitial fibroblasts in myocardial infarction; however, the activation mechanism also remains unknown." (PMID 35740305, 2022). "Additionally, priming MSCs with a cocktail of growth factors including FGF-2, IGF-1, and bone morphogenetic protein-2 (BMP-2) improved cardiac function in a rat model of myocardial infarction." (PMID 35008675, 2021). "Although inhibitory effects of BMP-2 on fibroblast function have been reported, the significance of such actions in repair following myocardial infarction and in cardiac fibrosis remains unclear." (PMID 31620450, 2019). "Following myocardial infarction, BMP2 shows an early time course of upregulation." (PMID 31620450, 2019). "Very little is known regarding the function of endogenous BMP-2 in myocardial infarction." (PMID 31620450, 2019). "Our data are consistent with other studies in myocardial infarction-associated heart failure, indicating that BMP2 could exert a negative role of cardiac fibrosis in different cardiovascular diseases." (PMID 39334820, 2024). "In a model of non-reperfused myocardial infarction, transient early induction of BMP2 was followed by increased expression of other BMPs." (PMID 31620450, 2019). "Angiogenic effects of BMP2 have been documented in vitro and in vivo; however, the potential role of BMP2 as a regulator of neovessel formation in healing myocardial infarction has not been investigated." (PMID 31620450, 2019). "Also, BMP2 has been proven to exert cytoprotective effects on cardiomyocytes via reducing inflammation in a model of non-reperfused myocardial infarction." (PMID 39334820, 2024). "Thus, with regards to apoptosis induction after myocardial infarction, SMAD family members may either be detrimental, as under TGFβ-stimulation, or confer protective effects as shown under BMP2-stimulation." (PMID 25788886, 2015).
non-small cell lung carcinoma (10 papers, 2011 to 2024). A group of at least three distinct histological types of lung cancer, including non-small cell squamous cell carcinoma, adenocarcinoma, and large cell carcinoma. "Serum levels of BMP2 are used as a prognostic indicator in non-small cell lung cancers (NSCLCs), in which increased serum levels correlate with advanced clinical stage." (PMID 27494873, 2016). "Using quantitative real-time RT-PCR, BMP-2 mRNA expression was detected in 61 non-small cell lung cancer (NSCLC) samples." (PMID 24946687, 2014). "By contrast, BMP proteins are highly over-expressed in human non-small cell lung carcinoma and recombinant BMP-2 enhances the growth of tumors formed from A549 cells injected subcutaneously into nude mice." (PMID 22168923, 2011). "The expression of BMP-2 is altered in solid tumors comparing to neighboring normal tissue, eg. increased expression in pleomorphic adenoma of salivary glands, non-small cell lung carcinomas and reduced expression in microadenomas of familial adenomatous polyposis." (PMID 26340447, 2015). "Results from our gene expression profiling study are in broad agreement with previous studies performed on non-small-cell lung cancer (NSCLC) and head and neck squamous cell carcinoma (HNSCC), where greater than 95% of cases have been shown to overexpress BMP2, phosphorylated SMAD1/5, and Id1." (PMID 32708289, 2020). "BMP-2 is highly expressed in the majority of non-small cell lung carcinomas (NSCLC) but not in normal lung tissue or benign lung tumors." (PMID 23593444, 2013).
Arthritis (9 papers, 2009 to 2022). Inflammation of a joint. "Functional enrichment further supported that the primed genes are heavily involved in inflammatory response, arthritis-promoting functions (Ccl2, Cxcl5, Sphk1) and, interestingly, Wnt pathway (Bmp2, Rspo3, Cd44) and stem cell differentiation (Sox5, Nrp2, Cdk6)." (PMID 35879783, 2022). "Using the same assay, one study showed that serum BMP2 levels were undetectable in patients with femoral fractures, whereas in another study, serum BMP2 and −7 levels could be detected in patients with ankylosing spondylitis, arthritis and healthy subjects." (PMID 23627969, 2013). "In our study, BMP2 and BMP7 were downregulated within the arthritic paw, which is similar to findings in the collagen-induced arthritis model." (PMID 26801240, 2016). "The increased expression and production of specific BMPs (i.e., BMP2, BMP6, and BMP7) in the synovium and synovial fluid of patients with RA as well as in mouse models of arthritis have been reported by different groups." (PMID 26215036, 2015). "Besides, bone morphogenetic proteins (BMPs, e.g., BMP2 and BMP4), potent mediators for osteoblast differentiation, were strongly over-expressed in the tissues from MBL−/− arthritis mice compared to those from WT counterparts." (PMID 31214191, 2019). "Several BMP ligands, including BMP2, BMP6, and BMP7, have been shown to be upregulated in the synovium of patients with RA as well as in tumor necrosis factor-alpha (TNF-α) transgenic mice developing arthritis and in collagen-induced arthritis models." (PMID 26215036, 2015). "The expression of bone morphogenetic protein 2 (BMP2) and BMP7, which may act as osteoblast growth factors, was not increased in DTHA compared with paws of untreated naive mice, but it seemed to decrease upon arthritis induction." (PMID 26801240, 2016).
Hypertension (9 papers, 2019 to 2025). The presence of chronic increased pressure in the systemic arterial system. "Our study demonstrated that interactions between rs17563 (BMP4) and rs235756 (BMP2) influence hypertension risk." (PMID 39997941, 2025). "Analysis identified a significant association at the rs1005464 of the BMP2 and hypertension risk, with AIC and BIC criteria confirming a dominant inheritance pattern." (PMID 39997941, 2025). "The BMP2/4 genes have been identified as potential candidates for genetic polymorphisms associated with hypertension." (PMID 39997941, 2025). "The significance of the SNPs selected in this study on bone-related disorders has been demonstrated by thorough research in a wide range of individuals, so this postulates a mechanism: BMP2/4 gene mutations enhance hypertension risk with fluoride exposure." (PMID 39997941, 2025). "The rs1005464 (G > A) polymorphism of the BMP2 gene was associated with an increased risk of hypertension." (PMID 39997941, 2025). "The rs1005464 (G > A) polymorphism of BMP2 was identified as a protective factor against hypertension in individuals with the AG + AA genotype." (PMID 39997941, 2025). "While many studies have suggested a relationship between fluoride exposure and hypertension risk, few have provided epidemiological evidence on the specific role of BMP2/4 gene polymorphisms in this association." (PMID 39997941, 2025). "Most of the patients in both groups were women (72% in TCP + IBG and 70% in BMP-2) and hypertension was the most common underlying disease." (PMID 37337174, 2023). "This study hypothesizes that specific polymorphisms in BMP2/4 may contribute to the susceptibility to hypertension, potentially modifying vascular function and response to environmental exposures such as fluoride." (PMID 39997941, 2025). "A study on middle-aged Finnish men found a significant association between the BMP2 gene variant (rs235756) and the BMP4 gene variant (rs4901417) were associated with hypertension." (PMID 39997941, 2025). "Significant interactions were observed between the BMP2 rs1005464 and BMP4 rs17563 polymorphisms, influencing hypertension risk." (PMID 39997941, 2025). "Valve cusps, thought to be stretched considerably through hypertension, expressed high levels of BMP2 and 4 in vitro and when noggin, an inhibitor for BMP2 and 4, was introduced, the resulting calcification was diminished in a concentration-dependent matter." (PMID 32781528, 2020). "BMP2 gene polymorphisms affect the risk of hypertension, and BMP4 gene polymorphisms may modify the impact of fluoride on hypertension." (PMID 39997941, 2025). "Additionally, an interaction was discovered between the BMP2 rs1005464 polymorphism and the BMP4 rs17563 polymorphism in relation to hypertension." (PMID 39997941, 2025). "The overexpression of BMP-2 may lead to renal injury and hypertension in CKD patients, whereas the elevated concentration of TGF-β1 may be the main pathogenic factor driving glomerular and tubulointerstitial fibrosis in the kidney." (PMID 39054437, 2024). "The development of renal damage, hypertension, and increased pulse wave velocity (PWV) in CKD might be associated with an imbalance in bone morphogenetic proteins (BMP)-2 and BMP-7." (PMID 36613483, 2022). "Against this background, we hypothesize that an imbalance in BMP-2 and BMP-7 occurs at CKD stages I-III associated with the development of hypertension, vascular stiffness, and progressive kidney damage." (PMID 36613483, 2022). "Moreover, in diabetic models, BMP4 disturbs blood flow and activates arterial NOXs, phenomena that promote ROS-induced inflammation, endothelial dysfunction and hypertension; BMP2 induces endothelial calcifications via WNT-MSX2." (PMID 31561501, 2019).
Hypertension (continued). "BMP2 and BMP4 are particularly important in vascular smooth muscle cell (VSMC) trans-differentiation, a process that leads to the loss of muscle characteristics, increased expression of bone-related proteins, and vascular calcification, all of which are linked to hypertension." (PMID 39997941, 2025). "Indoxyl sulphate: Parallel to inducing vascular calcification, indoxyl sulphate administration to human VSMC or rats with hypertension or 5/6 nephrectomy increased the expression of CBFA1/RUNX2, ALP, BMP2 and osteopontin, while a reduction in α-SMA, SM22-α and/or SMTN expression could be observed." (PMID 33172085, 2020). "Moreover, BMP2/4 administration induces O2− generation, endothelial dysfunction and hypertension in systemic arteries but does not affect pulmonary blood vessels." (PMID 31561501, 2019).
breast tumor (8 papers, 2017 to 2024). "Matched BC patient samples of primary breast tumor and bone metastasis tissues were compared for gene expression in the bone, where bone morphogenetic protein 2 (BMP2) was most significantly upregulated." (PMID 38193534, 2024). "To further examine the role of ID4 in cancer stemness, we knocked down ID4 in MDA-MB-468 breast tumor cells using SMARTpool siRNAs, and tested the expression of a panel of stemness genes including Twist1, Twist2, Snail, Slug, BMP2, IRF1, SOX4, Foxk1 and Notch3." (PMID 36291790, 2022). "This hypothesis is supported by the significant number of histopathological studies demonstrating altered expression of mineralisation associated proteins including BMP2, osteopontin, RUNX2, and TRPM7 in breast tumours with associated microcalcifications." (PMID 30679450, 2019). "A recent literature review has highlighted that BMP2 enhanced angiogenesis through endothelial cells, whilst BMP9 and BMP10 inhibited cell growth and tumour angiogenesis in breast tumours." (PMID 37333824, 2023). "Although macrophages have been shown to express BMPs during breast tumor progression and produce microcalcifications in breast tissue, the hypoxic preconditioning of PBCs (containing monocytes) did not result in measurable levels of BMP-2 and -7 in HPS." (PMID 38791352, 2024).
calcification (8 papers, 2013 to 2024). Process by which organic tissue becomes hardened by the physiologic deposit of calcium salts. "In in-vivo models of arterial calcification, BMP-2 gene expression is upregulated in the aortic adventitia and atherosclerotic plaques." (PMID 29895327, 2018). "Since both the BMP2 and MGP participate in the process of arterial calcification, we observed the expressions of BMP2 and MGP in calcified radial arteries of hemodialysis patients." (PMID 23506394, 2013). "Therefore, inhibiting the pathological increase of BMP2 may be a potential strategy in the pharmacological intervention of vascular calcification in CKD." (PMID 32954678, 2020). "In conclusion, our data for the first time demonstrate that celastrol attenuates high calcium–induced arterial and valvular calcification by inhibiting BMP2/Smad1/5 signalling, which may provide a novel therapeutic strategy for arterial and valvular calcification in patients with CKD." (PMID 32954678, 2020). "In particular, the expression of nuclear factor kappa B (NF-κB) and bone morphogenetic protein 2 (BMP-2) is significantly increased in individuals with aortic stenosis, favoring both inflammation and valvular calcification." (PMID 39840161, 2024).
chondrosarcoma (8 papers, 2010 to 2019). A malignant cartilaginous matrix-producing mesenchymal neoplasm arising from the bone and soft tissue. "The results suggested that intrinsically BMP4 was more potent than BMP2 at 10-20 ng/ml in SW 1353 chondrosarcoma cells." (PMID 31326745, 2019). "We provide evidence suggesting that TIMP3, IGFBP5, and BMP2 are direct targets of Gli-mediated Hh signaling with implications for chondrosarcoma pathology, including potential cross-talk between TGF-beta signaling and Hh signaling." (PMID 30695055, 2019). "A study demonstrated that UPS-regulated NF-κB signaling in bone morphogenetic protein-2-activated β1 integrin expression promotes the migration of human chondrosarcoma cells." (PMID 30586948, 2018). "The migratory effect of BMP2 on chondrosarcoma cell lines, however, suggests a role of BMP signaling in progression." (PMID 23088614, 2012). "Using DNA affinity chromatography followed by mass spectrometry, we recently observed fragments of the Bmp2 proprotein in nuclear extracts from rat chondrosarcoma (RCS) cells." (PMID 20230640, 2010). "Compared to normal cartilage, chondrosarcoma showed altered expression levels for BMP2 and BMP7." (PMID 23088614, 2012). "Previous reports have indicated that TGF-β and BMP-2, both highly homologous to BMP-7, are able to enhance cell motility and αvβ3 integrin expression in human chondrosarcoma cells, via pathways involving PI3K, Akt, and NF-κB." (PMID 25390068, 2014). "While one immunohistochemical study found no BMPs in human conventional chondrosarcoma tissue, one RT-PCR based gene expression analysis detected expression of BMP2, 4, 6 and BMPRII." (PMID 23088614, 2012).